WFDC13 (WAP four-disulfide core domain 13)
Description:
Putative acid-stable proteinase inhibitor.
Synonyms: C20orf138; WAP13; dJ601O1.3
Tractability: Antibody: UniProt places it where antibodies can reach, with high confidence; UniProt predicts a signal peptide or a membrane-spanning region; its Gene Ontology location is reachable by antibodies, with medium confidence.
Gene: Protein-coding gene on chromosome 20 (45,702,038 to 45,708,817, forward strand). Ensembl gene ENSG00000168634.
Subcellular location: Secreted
Gene Ontology:
Molecular function: protein binding; serine-type endopeptidase inhibitor activity
Biological process: antibacterial humoral response; innate immune response
Cellular component: extracellular region
Genetic constraint (gnomAD): Loss-of-function variants: 6 observed, 11.53 expected, observed/expected ratio (o/e) 0.52, 90% interval 0.28 to 1.03. The upper end of that interval is the gene's LOEUF score, 1.03, which puts it in group 4 of 6, group 1 being the genes least tolerant of losing a copy. Missense variants: 104 observed, 115.07 expected, observed/expected ratio (o/e) 0.9, 90% interval 0.77 to 1.06. Synonymous variants: 38 observed, 41.84 expected, observed/expected ratio (o/e) 0.91, 90% interval 0.7 to 1.19.
Homologues: Orthologues: chimpanzee WFDC13 (100% identical), macaque WFDC13 (90% identical), rabbit WFDC13 (61% identical), dog WFDC13 (57% identical), guinea pig WFDC13 (52% identical), mouse Wfdc13 (48% identical), Drosophila melanogaster CG5639 (17% identical), Caenorhabditis elegans C08G9.2 (16% identical). Paralogues in human: WFDC10A (27% identical), WFDC10B (24% identical), SLPI (23% identical), WFDC9 (23% identical), WFDC3 (20% identical), PI3 (19% identical), WFDC11 (19% identical), WFDC5 (19% identical), WFDC12 (18% identical).
Diseases named in the same sentence as WFDC13 in open-access papers:
WFDC13 is named in the same sentence as 5 diseases in open-access papers, as found by Europe PMC text mining. Sharing a sentence is not in itself a finding about the gene and the disease. The quoted sentences say what the papers report.
colon cancer (1 paper, 2025). "Our experiments confirmed that PAN3-AS1 facilitated WFDC13 expression through competitive binding to hsa-miR-423-5p in colon cancer." (PMID 41502505, 2025). "Addressing the PAN3-AS1/miR-423-5p/WFDC13 axis might provide a novel option for improving immunotherapy efficacy in colon cancer." (PMID 41502505, 2025).
melanoma (1 paper, 2025). A malignant, usually aggressive tumor composed of atypical, neoplastic melanocytes. "Meanwhile, the Kaplan-Meier Plotter database showed that WFDC13, highly expressed in melanoma and BLCA patients, indeed had a poor prognosis when they received anti-PD1, anti-PDL1, or anti-CTLA4 antibodies (Fig. A4A)." (PMID 41502505, 2025).
ovarian carcinoma (1 paper, 2025). A malignant neoplasm originating from the surface ovarian epithelium. "Additionally, WFDC13 was found to be a fusion gene in ovarian carcinoma." (PMID 41502505, 2025).
tumor (1 paper, 2025). "By a coculture system, we found that CD8+ T cells with PAN3-AS1 or WFDC13 knockdown tumor cells exhibited higher granzyme B production and enhanced Ki67 activity." (PMID 41502505, 2025). "For instance, how does WFDC13 regulate the tumor microenvironment?" (PMID 41502505, 2025).
WFDC13 also shares sentences with these, for which no sentence is quoted: pancreatic cancer (1 paper).